PARP1 (poly(ADP-ribose) polymerase 1)
Diseases named in the same sentence as PARP1 in open-access papers (continued):
Sharing a sentence is not in itself a finding about the gene and the disease.
rhabdomyosarcoma (6 papers, 2016 to 2022). A rare aggressive malignant mesenchymal neoplasm arising from skeletal muscle. "The PARP1 inhibitor, olaparib, inhibited the proliferation of malignant peripheral nerve sheath tumor cells and another PARP1 inhibitor, rucaparib, induced apoptosis and inhibited the proliferation of rhabdomyosarcoma cells." (PMID 27643881, 2016). "We hypothesized that due to its effect on BRCA1 phosphorylation and HR activity, pharmacological ATR inhibition could sensitize rhabdomyosarcoma cells to PARP1 inhibition." (PMID 35879366, 2022). "It would also be interesting to examine the possible role of PARP1-dependent chromatin alterations in muscle pathologies, such rhabdomyosarcoma, in which the failure to activate some myogenic targets correlates with the defective MyoD binding to their regulatory regions." (PMID 32934320, 2020). "The epistatic relation of PARP1 and Tdp1 in the repair of topotecan/irinotecan stabilized Topo1cc’s was highlighted in Rhabdomyosarcoma cells treated with PARP1-inhibitor and Tdp1 knockdown, and DT40tdp1-/- cells treated with combinations of PARP1-inhibitor and CPT." (PMID 31698852, 2019). "Interestingly, a combination of TDP1 knockdown and PARP1 inhibition has been shown to be cytotoxic in rhabdomyosarcoma cells even without BRCA alterations." (PMID 34300575, 2021).
squamous cell carcinoma (6 papers, 2012 to 2025). A carcinoma arising from squamous epithelial cells. "The data of squamous cell carcinoma and adenocarcinoma in TCGA indicated significant higher expression of PARP1 in tumor tissues." (PMID 29152079, 2017). "In human squamous cell carcinoma SAS cells, BNCT treatment led to the activation of caspase-9 and caspase-3, as well as the cleavage of poly (ADP-ribose) polymerase-1 (PARP-1) and phosphorylated histone H2AX (γH2AX)." (PMID 41179690, 2025).
thyroid cancer (6 papers, 2017 to 2021). "Histological subtype analysis showed the significant association of selected PARP1 SNPs with papillary, follicular and anaplastic subtypes in thyroid cancer patients." (PMID 30183716, 2018). "In this study, we investigated the association of three PARP1 gene polymorphisms i-e Val762Ala (rs1136410), Ala284Ala (rs1805414) and Asp81Asp (rs1805404) with thyroid cancer susceptibility." (PMID 30183716, 2018). "In case of third polymorphism of PARP1 gene Asp81Asp (rs1805404), frequency of minor allele homozygote was observed significantly higher in controls compared to thyroid cancer patients and showed inverse association with the said disease." (PMID 30183716, 2018). "The present study was designed to explore the link between the PARP1 polymorphisms and thyroid cancer risk." (PMID 30183716, 2018). "Next, we illustrated the mechanism underlying how SCL6A9 and PARP-1 influenced the tolerance of thyroid cancer cells under 131I exposure." (PMID 28086241, 2017). "For second selected SNP of PARP1 gene Ala284Ala (rs1805414), in cancer patients there was higher minor allele frequency than in controls and has significant effect on increasing the risk of thyroid cancer in current study." (PMID 30183716, 2018). "Therefore, to explore the reliable influence of these SNPs of PARP1 on thyroid cancer, mutational analysis in thyroid cancer patients and healthy controls has been planned to assess the active involvement of these polymorphisms in carcinogenesis." (PMID 30183716, 2018). "TD139 induced apoptosis of thyroid cancer cells, as evident by an increase in the percentage of sub-G1 cells on cell cycle analysis, caspase-3 activation, and PARP1 cleavage." (PMID 34035807, 2021). "In conclusion, this study demonstrated that SLC6A9 is downregulated in 131I-resistant thyroid cancer accompanied by PARP-1 inhibition." (PMID 28086241, 2017). "In patients with thyroid cancer, a positive correlation between SLC6A9-5:2 and PARP-1 was identified, and low SLC6A9-5:2 expression was associated with a worse prognosis of papillary thyroid carcinoma." (PMID 28086241, 2017). "Higher SLC6A9 expression significantly increased PARP-1 expression in thyroid cancer cells and was accompanied by effective 131I treatment." (PMID 28086241, 2017). "After downregulating SLC6A9 or blocking PARP-1 artificially, the sensitive thyroid cancer cells mostly displayed a tolerant phenotype under 131I exposure." (PMID 28086241, 2017). "Additionally, as far as we know, neither any study was carried out to analyze the combined effect in the form of haplotype analysis of Val762Ala (rs1136410), Ala284Ala (rs1805414) and Asp81Asp (rs1805404) SNPs of PARP1 gene in thyroid cancer previously." (PMID 30183716, 2018). "Furthermore, SLC6A9-5:2 overexpression was positively correlated with PARP-1 mRNA and protein levels, which restored the sensitivity of resistant thyroid cancer cells." (PMID 28086241, 2017). "Furthermore, we pretreated PTC cells with the PARP-1 inhibitor 3-AB for 12h, 24h and 48h before 131I treatment, significantly protecting thyroid cancer cells from ATP exhaustion." (PMID 28086241, 2017). "Therefore, our present study was focused on the relationship between 131I sensitivity in thyroid cancer cell lines with PARP-1 activity." (PMID 28086241, 2017). "Furthermore, our analyses revealed high SLC6A9 and SLC6A9-1 expression promote PARP-1 function in thyroid cancer." (PMID 28086241, 2017). "Furthermore, transfection of SLC6A9-1 into resistant thyroid cancer cells also enhanced the expression of PARP-1, PAR and γH2AX, indicating more active DNA repair." (PMID 28086241, 2017). "However, in our study, PARP-1 inhibition dramatically protected the thyroid cancer cells from radioactive therapy to a great extent." (PMID 28086241, 2017). "Thus, we further focused on how PARP-1 inhibition could protect thyroid cancer cells from 131I injury." (PMID 28086241, 2017).
thyroid cancer (continued). "Therefore, our results imply that SLC6A9 acts as a stabilizer for 131I sensitivity by maintaining PARP-1 expression and may serve as a novel therapeutic agent for thyroid cancer patients with 131I treatment failure." (PMID 28086241, 2017). "However, till now only one study has been reported with respect to PARP1 gene polymorphism and thyroid cancer subtype and no significant change in crude/adjusted OR of Val762Ala polymorphism of PARP1 gene, has been revealed in either papillary or follicular thyroid cancer subgroups." (PMID 30183716, 2018). "We demonstrated that SLC6A9-5:2 was remarkably downregulated in 131I-resistant thyroid cancer cell lines and 131I-insensitive patients and was positively correlated with Poly (ADP-ribose) polymerase 1 (PARP-1) expression and its activation." (PMID 28086241, 2017). "However, the exact role of PARP-1 in thyroid cancer 131I sensitivity has not yet been elucidated." (PMID 28086241, 2017).
type 1 diabetes (6 papers, 2010 to 2026). "Functional validation was conducted using the PARP1 inhibitor PJ-34 and PARP1 gene silencing in vitro and in a streptozotocin-induced type 1 diabetic mouse model." (PMID 41847180, 2026). "PARP1 knockout in Type I diabetes mellitus (T1DM) mouse models underwent ligation of the carotid artery to induce neointimal hyperplasia." (PMID 39153052, 2024). "Among PARPs, PARP-1 has attracted a great deal of attention because of its relevance to the development of type 1 diabetes and its complications." (PMID 20804590, 2010). "This methylnitrosoureido derivative of D-glucose is well suited as pharmacological tool for studying the effects of compounds with PARP-1 inhibitory action and with potential for preventing the onset of type 1 diabetes in experimental animals." (PMID 20804590, 2010). "Noteworthy, ROS-mediated PARP-1 over-activation is able to induce cell death by necrosis; furthermore, it has been demonstrated that in a mouse model of type 1 diabetes, beta cells die by necrosis in a process of programmed cell death that requires both apoptosis and necroptosis." (PMID 29324687, 2018).
adenoma (5 papers, 2008 to 2022). A neoplasm arising from the epithelium. "However, evidence that PARP1 is intimately associated with CRC came from 91 analyzed tumors, of which PARP1 mRNA overexpression was observed in 64 (70.3%) at the early stages of CRC (65 adenomas and 26 submucosal carcinomas, respectively)." (PMID 36230796, 2022). "Protein and mRNA levels of PARP-1 in adenoma and carcinoma tissues differ; the mRNA level is lower in adenoma than in carcinoma, while the protein level is similar in both tissues." (PMID 25526641, 2014). "Adenoma tissue contained almost 10 times greater amount of PARP-1 protein than normal colon (6.4, range 5.0–9.0 in adenoma versus 0.66, range 0.2–1.2 in normal colon, p<0.00001)." (PMID 25526641, 2014). "A correlation between PARP-1 and OGG1 proteins content was found in adenoma tissues (r = 0.5697) and tumor tissues (r = 0.3645)." (PMID 25526641, 2014). "Interestingly, the number of cells positively stained for PARP-1 and OGG1 was lower in adenoma tissues than in cancerous ones, although the intensity of staining was much stronger in polyps than in cancerous tissues." (PMID 25526641, 2014). "This might reflect increased 8-oxoGua elimination from DNA, which would be consistent with the significant increase in OGG1 and PARP-1 protein in adenoma and carcinoma tissues in relation to normal colon tissue of CRC patients." (PMID 25526641, 2014). "Unfortunately, the material obtained from adenoma patients did not contain well distinguished normal colon tissue which could be seen in histological sections as marginal tissue, and would enable to measure PARP-1 and OGG1 proteins in adenoma and normal colon from the same patient." (PMID 25526641, 2014).
chordoma (5 papers, 2016 to 2025). Chordomas are rare malignant tumors arising from embryonic remnants of the notochord in axial skeleton. "While PDGFRB and PARP1 inhibitors have been applied as chordoma therapies, the biological and clinical role of the other candidates is unclear." (PMID 40901948, 2025). "SOX9 (n=4, p=0.04), whose knockdown was previously shown to inhibit chordoma cell growth and induce apoptosis, and PARP1 (n=5, p=0.004) and Survivin (n=3,p=0.047), also critical to chordoma cell growth, all show decreased expression with selinexor treatment." (PMID 36059685, 2022). "Here, the authors identify molecular alterations associated with defective homologous recombination DNA repair in advanced chordomas and report prolonged response in a patient treated with a PARP inhibitor, which later acquired resistance due to a newly gained PARP1 mutation." (PMID 30967556, 2019).
chronic myelogenous leukemia (5 papers, 2015 to 2025). "Outside of EBV, a similar mechanism was reported in PARP1-deficient chronic myelogenous leukemia cells, which showed reduced HIF-1 transcriptional activation dependent on PARP1 enzymatic activity." (PMID 30395643, 2018). "In addition, PARP1-deficient chronic myelogenous leukemia cells showed reduced HIF-1 transcriptional activation dependent on PARP1 enzymatic activity." (PMID 30395643, 2018). "Previous studies using HAP1 chronic myelogenous leukemia cells found that FAM111A depletion sensitizes cells to PARP1 inhibitors." (PMID 40446667, 2025). "For example, myeloproliferative diseases (excluding chronic myeloid leukemia, CML) have the most colocalized genes, including RPN1, BRAP, PPP1CC, ERP29, and PARP1." (PMID 41048997, 2025). "In chronic myelogenous leukemia (CML) cell line, K562, alantolactone treatment resulted in apoptosis induction by activating caspase-3 and poly (ADP-ribose) polymerase-1 (PARP-1) as well as the reduction of MMP in these cancer cells." (PMID 38529189, 2024).
coronary artery disease (5 papers, 2017 to 2025). "All these findings indicate that inhibition of PARP1 activation could be a novel potential therapeutic strategy against vascular diseases, including artery stenosis and coronary heart diseases." (PMID 40744995, 2025). "Thus, the findings to date indicate that the DNA damage-PARP1-NAD+ axis is also indicated in coronary artery disease and therefore may represent a novel target for therapeutic treatment." (PMID 32411727, 2020).
diabetic cardiomyopathy (5 papers, 2016 to 2023). Diabetic cardiomyopathy is a disorder of the heart muscle in people with diabetes. "PARP1 inhibition by vitamin D supplementation had protective effect against diabetic cardiomyopathy, partly through the PARP1/SIRT1/mTOR pathway." (PMID 37047134, 2023). "In line with the high glucose treated cardiomyocytes in vitro, PARP1 deletion in mice reduced the concentration of proinflammatory cytokines, decreased apoptosis, and enhanced activation of IGF-1R and AKT in the diabetic cardiomyopathy model." (PMID 34725336, 2021). "In human aortic ECs (HAECs) and HUVECs, high glucose also induces EndMT through positive regulators, such as angiotensin II, poly (ADP-ribose) polymerase 1 (PARP-1), endothelin 1 (ET-1), Smad, Akt, p38, and ERK, contributing to diabetic cardiomyopathy." (PMID 29515588, 2018).
diabetic nephropathy (5 papers, 2016 to 2026). "PARP1−/− gene deficiency alleviates diabetic kidney disease by using the PARP1 deficient mouse to evaluate the role of PARP1." (PMID 35806303, 2022). "Parp1 depletion protects against nephrotoxicity induced by the chemotherapeutic agent, cisplatin, diabetic nephropathy and the necrosis associated with renal ischemia/reperfusion." (PMID 27391435, 2016).
endotoxemia (5 papers, 2016 to 2022). "The data from PARP-1 inhibition studies suggest that LPS-induced endotoxemia causes the activation of this enzyme, followed by the induction of necrotic cell death and organ damage." (PMID 34826885, 2022). "During the present study, the effect of PARP-1 inhibitor 4-HQN on the changes of ovarian function in mice with endotoxemia was examined." (PMID 34826885, 2022). "Here, we find that PARP-1 inhibitors (3-AB) significantly inhibited LPS-induced cell death, suggesting the presence of parthanatos in endotoxemia." (PMID 34282120, 2021). "All these results indicate that TLR4 plays an significant role in parthanatos in the presence of LPS, and PARP-1 probably represents a latent new target for the treatment of endotoxemia." (PMID 34282120, 2021). "Additionally, it has been described previously that female and male mice exhibit different responses to Parp1 deletion or Parp inhibition in mouse models of endotoxemia and nephrotoxic serum-induced nephritis." (PMID 27391435, 2016). "In addition, 3-AB pretreatment also significantly improved survival in LPS-treated mice with indicating that PARP-1 might play a critical role in endotoxemia." (PMID 34282120, 2021). "In this respect, the effect of PARP-1 inhibitor, 4-HQN, on oocyte meiotic maturation, apoptotic and necrotic death, and also DNA integrity of granulosa cells in mice with LPS-induced endotoxemia was studied." (PMID 34826885, 2022).
fatty liver (5 papers, 2021 to 2024). "Genomic ablation or enzymatic inhibition of PARP1 is linked to the protection against fatty liver disease, increases in NAD+ levels, increased glycolysis, and reduced mitochondrial damage." (PMID 38932202, 2024). "Consistently, PARP1 inhibition rescued ALDH2 deficiency–induced fatty liver and elevated HDL-C in AKO mice." (PMID 35393951, 2022). "The WD-induced fatty liver due to ALDH2 deficiency was significantly prevented with PARP1 inhibition." (PMID 35393951, 2022). "Inhibition of PARP1 activation reduces lipid accumulation and the inflammation of fatty liver in mice." (PMID 34684653, 2021). "A recent study has revealed that aging-related fatty liver induced by the dysregulation of O-GlcNAcylation is closely associated with aminoacyl tRNA synthetase complex-interacting multifunctional protein 2 (AIMP2) and poly (ADP-ribose, PAR) polymerase 1 (PARP1)." (PMID 38786029, 2024). "The inhibition of PARP-1 can increase NAD+ content and SIRT1 activity, enhance lipid metabolism, and improve hepatic steatosis in hepatocytes under oxidative stress and mice fed a high-fat diet." (PMID 34393826, 2021). "Puerarin can protect against hepatic steatosis, inflammation, and fibrosis, and improve NAFLD by regulating PARP-1/PI3K/AKT signaling pathway in male C57BL/6J mice." (PMID 34393826, 2021). "The inhibition of PARP-1 can activate the PI3K/AKT pathway to down-regulate the expression of the fat synthesis gene SREBP-1c, reduce lipid synthesis and accumulation, and improve fatty liver disease in HFHS diet mice." (PMID 34393826, 2021). "In addition, inhibition of PARP-1 can also increase NAD+ content and SIRT1 activity, enhance lipid metabolism, and improve hepatic steatosis in mice fed a high-fat diet." (PMID 34393826, 2021).
Hepatic fibrosis (5 papers, 2020 to 2025). The presence of excessive fibrous connective tissue in the liver. "Still, the overactivation of PARP-1, occurring by exposure to CCl4 is culprit for the pathophysiological mechanism of hepatic fibrosis." (PMID 38239200, 2023).
HIV-1 infection (5 papers, 2015 to 2022). The type species of lentivirus and the etiologic agent of acquired immunodeficiency syndrome (AIDS). "In human immunodeficiency virus 1 (HIV-1) infection, PARP1 activation increases the integration of the HIV-1 genome into the host chromosome." (PMID 35095818, 2021). "Overall effects of PARP1 on regulation of viral replication can be either proviral or antiviral, while the effects appear to be both in HIV-1 infection." (PMID 35095818, 2021). "In addition, drugs targeting DNA methyltransferases, COX1, PARP1, guanylyl cyclase, and menin binding reduced HIV-1 infection." (PMID 28114951, 2017). "Additionally, we also observed increased expression of both cleaved PARP-1, Caspase-3, and BAD in response to HIV-1 infection." (PMID 35132117, 2022).
metastatic prostate carcinoma (5 papers, 2008 to 2026). A carcinoma that arises from the prostate gland and has spread to other anatomic sites. "Recent findings showing frequent germline mutations in DNA homologous recombination genes within a metastatic prostate cancer cohort suggests the potential application of targeted therapies, such as PARP1-inhibition and platinum-based chemotherapy." (PMID 28878254, 2017). "The TALAPRO series of clinical trials is investigating the other PARP-1/2 selective inhibitor talazoparib to treat men with metastatic prostate cancer." (PMID 35205654, 2022). "A male patient with metastatic prostate cancer and a BRCA2 mutation has responded well to a PARP1 inhibitor (A Tutt, J De Bono, personal communication)." (PMID 18577985, 2008).
myelodysplastic syndrome (5 papers, 2017 to 2023). A clonal hematopoietic disorder characterized by dysplasia and ineffective hematopoiesis in one or more of the hematopoietic cell lines. "We measured PARP1 mRNA levels by a SYBR-green-based PCR in the bone marrow of 74 patients with myelodysplastic syndrome (MDS) and correlated them to their demographic, hematologic and prognostic characteristics." (PMID 28212373, 2017). "In addition, mutations in the core cohesion complex gene STAG2 (Stromal Antigen 2) induce DNA damage, stalled replication forks and a high genetic dependency on PARP1 in AML/myelodysplastic syndrome (MDS) cells." (PMID 36497275, 2022).
oral squamous cell carcinoma (5 papers, 2018 to 2024). "Oxaliplatin induces the PARP1-mediated parthanatos in oral squamous cell carcinoma by increasing production of ROS." (PMID 37469162, 2024). "In oral squamous cell carcinomas, overexpression of PARP-1 may serve as novel predictive biomarker for therapy responsiveness." (PMID 33572586, 2021).